KRAS (KRas proto-oncogene, GTPase)
Diseases named in the same sentence as KRAS in open-access papers (continued):
Sharing a sentence is not in itself a finding about the gene and the disease.
lung adenocarcinoma (continued). "Moreover, frequent decrease of FSTL1-BMP4-p-Smad1/5/8-Smad4 pathway observed in smokers and in ALK-fusion or KRAS mutant adenocarcinoma patients may facilitate the understanding of the molecular pathogenesis of lung adenocarcinoma." (PMID 28852126, 2017). "Prognoses of lung adenocarcinoma patients with BMs are often associated with gene mutation status, including mutations in the epidermal growth factor receptor (EGFR), anaplastic lymphoma kinase-rearranged (ALK), and V-Ki-ras2 Kirsten rat sarcoma viral oncogene homolog (kRAS)." (PMID 29050314, 2017). "Frequent decrease of FSTL1 expression in adenocarcinoma with KRAS mutation or ALK fusion and in smokers implies that FSTL1 has a critical role and may be a potential therapeutic target for some specific molecular types of lung adenocarcinoma." (PMID 28852126, 2017). "Therefore, we aimed to explore the potential imaging characteristics of the main tumor and intra-thoracic findings, as well as metastases and infiltration patterns, among patients with advanced-stage (stage IIIB–IV) lung adenocarcinoma and driver mutations in EGFR, KRAS, or ALK." (PMID 27518729, 2016). "Interestingly, in a Chinese population composed of patients with lung adenocarcinomas who are also smokers, the incidence of KRAS mutations was found to be 14.0 %, while that of non-smokers was 3.4 %." (PMID 27655296, 2016). "On the other hand, studies with KrasLA1 mice, which develop lung adenocarcinoma through somatic activation of a KRAS allele carrying an activating mutation in codon 12 suggested that the presence of KRAS mutations was not sufficient to confer resistance to EGFR inhibition." (PMID 27458163, 2016). "In this study, we analyzed exome sequencing data from 16 EGFR/KRAS/ALK-negative tumors and paired normal samples and an applicable expansion cohort of 54 EGFR/KRAS-negative lung adenocarcinomas to identify novel somatic mutations in lung adenocarcinomas of never-smokers." (PMID 24576404, 2014). "We selected formalin-fixed paraffin embedded lung adenocarcinoma specimens that showed discrete areas of different subtypes, extracted subtype DNA samples from those areas and screened for mutations in hotspot regions of the EGFR, KRAS and BRAF genes using high resolution melting." (PMID 24742923, 2014). "Interestingly, although somatic mutation is rare in EGFR/KRAS/ALK-negative lung adenocarcinoma of never-smokers, the PCDHB14 (cell adhesion) Y670S mutation and YTHDF1 (RNA binding) I492V mutations were each found in two cases (12.5%)." (PMID 24576404, 2014). "To identify copy number alterations (CNAs) of general importance in lung adenocarcinoma, which may serve as basis for supervised comparisons between EGFR-mutated, KRAS-mutated and EGFRwt/KRASwt tumors, we analyzed 1272 tumors and cell lines profiled by SNP or aCGH microarrays." (PMID 24205279, 2013). "However, only the association with EGFR mutation was replicated in the TCGA data, suggesting loss of DOK2 is associated with EGFR mutation but not KRAS mutation in human lung adenocarcinoma." (PMID 24255704, 2013). "In another study with 183 lung adenocarcinomas, MET amplification was observed in 8 (4%) patients with wild-typed EGFR and wild-typed KRAS, indicating that the presence of MET gene amplification might be mutually exclusive with EGFR and KRAS mutations." (PMID 27234388, 2013). "We determined the mutational status and copy numbers of KRAS gene for 288 lung adenocarcinoma tumors including Non-Asian (n = 127) and Asian (n = 161) populations obtained from five different institutions and correlated the data with clinical and other findings." (PMID 19826477, 2009). "Concurrent KRAS + STK11 alterations were identified in 23.5% of cases, compared with The Cancer Genome Atlas (TCGA) cohorts of other lung adenocarcinomas (11/566, 2.0%) and HCC (0/372, 0%)." (PMID 42096087, 2026).
lung adenocarcinoma (continued). "Among the hotspot amplifications were the regions encompassing EGFR (ch7p11),KRAS (ch12p12), and MCL1 (ch1q21), which are well-recognized cancer drivers that play crucial roles and are known to be amplified in lung adenocarcinoma." (PMID 40867048, 2025). "Proteomic and phosphoproteomic analyses were performed on lung adenocarcinoma (LUAD) tumors with EGFR, KRAS, or EML4–ALK alterations and wild‐type cases." (PMID 40621945, 2025). "To detect the correlation between KRAS and PTPN11, we screened the gene co‐expression of lung adenocarcinoma (LUAD) patients (n = 706) in TCGA database." (PMID 39992860, 2025). "To further confirm the role of CD103+ T cells during lung adenocarcinoma initiation, we adoptively transferred purified CD103− T cells or CD103+ T cells into WT‐KRAS (G12D) and Med23−/−‐KRAS (G12D) mice and induced the KRAS (G12D) expression after that." (PMID 40344646, 2025). "The top five actionable alterations in lung adenocarcinomas were reported in EGFR (43 %), ALK (5 %), BRAF (5 %), KRAS (5 %), and ROS1 (2 %) genes." (PMID 40821453, 2025). "Among KRAS mutations, the glycine‐to‐cysteine substitution at codon 12 (G12C) is the most frequent KRAS substitution in lung adenocarcinoma (LUAD), occurring in approximately 40% of KRAS‐mutant LUAD cases." (PMID 41025426, 2025). "KRAS is one of the principal driver tumor genes described in CRC and most of the deadliest types of cancer, such as pancreatic and lung adenocarcinomas." (PMID 39001385, 2024). "KRAS is one of the most prevalent oncogenic drivers in NSCLC, found in over 30% of lung adenocarcinomas based on data from the Cancer Genome Atlas." (PMID 38611005, 2024). "KRAS protein levels increased by 1.2-fold, whereas other RAS members remained unchanged in lung adenocarcinoma cells." (PMID 37626065, 2023). "In lung squamous cell carcinoma and lung adenocarcinoma, EZH2 expression is positively correlated with BRAF (r = 0.2397, p < 0.0001) and KRAS (r = 0.3167, p < 0.001) gene expression." (PMID 37069494, 2023). "The EZH2 gene expression of lung adenocarcinoma was positively correlated with the gene expression of BRAF (r = 0.2633, p < 0.0001) and KRAS (r = 0.31229, p < 0.0011)." (PMID 37069494, 2023). "Kirsten rat sarcoma viral oncogene homolog (KRAS) is one of the most common oncogenic drivers in NSCLC, seen in over 30% of lung adenocarcinomas (LUAD), depending on ethnicity and tumor stage and associated with smoking and female patients." (PMID 37835787, 2023). "Kirsten rat sarcoma viral oncogene homolog (KRAS) was also tested in NSCLC and occurs in about 26.1% of lung adenocarcinoma in Western countries." (PMID 37509345, 2023). "Mutation in the KRAS gene was found to be more frequent in B7H3-positive lung adenocarcinoma, however, data regarding CRC are missing, and the link between B7H3 and KRAS needs further research and explanation." (PMID 37370746, 2023). "In patients with KRAS-mutant lung adenocarcinoma (LUAD), SLC7A11 mediates cystine uptake, decreases ROS production and thus promotes lung adenocarcinoma proliferation and migration." (PMID 38273826, 2023).
lung adenocarcinoma (continued). "Gefitinib and Erlotinib (first-generation TKIs) exhibited no efficacy in lung adenocarcinoma patients with KRAS mutations, which could have been due to downregulation of VEGFR-2 in H2170-ER cells compared to H358-ER cells when both cell lines were exposed to Erlotinib." (PMID 35626731, 2022). "All six patients were diagnosed with lung adenocarcinoma and were wild‐type for EGFR, KRAS and ALK‐translocations." (PMID 36251951, 2022). "In lung adenocarcinoma, as reported, ILK can regulate KRAS, IPP complex and Ras suppressor-1 (RSU1) to promote cancer cell multiplication, migration and epithelial-mesenchymal transition (EMT), and its high expression is pertinent to poor prognosis." (PMID 35029589, 2022). "Among patients with lung adenocarcinomas, EGFR and KRAS were the highest discrepancy genes in the different racial groups (P<0.001)." (PMID 36248982, 2022). "Independent groups have reported DDR1 as a potential therapeutic candidate in KRAS-driven tumors, and combinatorial targeting of DDR1 has also been shown to be efficacious in KRAS-mutant tumors, lung adenocarcinoma, and recently pancreatic adenocarcinoma." (PMID 35664781, 2022). "Inhibition of miR-206 by RMRP was demonstrated to result in overexpression of KRAS, FMNL2, and SOX9 in lung adenocarcinoma, confirming RMPR as one of the KRAS-related lncRNAs." (PMID 34489556, 2022). "To examine in more detail the differentially active domains that we identified, we focused on the comparison between KRAS-driven and EGFR-driven lung adenocarcinoma, which exhibited the highest AUC ratio." (PMID 34344431, 2021). "In Ontario, testing for predictive biomarkers including EGFR for lung adenocarcinoma, BRAF in malignant melanoma and KRAS and BRAF in metastatic colorectal cancer supports the use of targeted therapies for these patients." (PMID 34597339, 2021). "In mouse lung adenocarcinoma cells, YAP1 was able to rescue KRAS depleted cells, suggesting a relevant mechanism to bypass loss of KRAS signaling." (PMID 32576853, 2020). "As expected, EGFR, ITGA2, KRAS, MMP9, NRAS and MAPK13 had higher levels in lung adenocarcinoma than in normal lung tissues." (PMID 32210363, 2020). "We first performed overall survival analysis to compare the survival of patients harboring mutant or wildtype KRAS in pancreatic adenocarcinoma (PAAD), lung adenocarcinoma (LUAD), and colorectal adenocarcinoma (COAD)." (PMID 33122197, 2020). "In the magnetic migration test the KRAS mutant A549 and the EGFR mutant PC-9 lung adenocarcinoma cell lines were used in 3D mono-cultures." (PMID 32434541, 2020). "Earlier, our research group established and characterized an in vivo mouse NSCLC tumor model system, with wild type KRAS and EGFR genes, mimicking the majority of human lung adenocarcinomas." (PMID 30734151, 2020). "We found that the expression of EZH2 is positively correlated with KRAS (r = 0.3167 and p < 0.001) and BRAF (r = 0.2397and p < 0.0001) gene expression in lung squamous cell carcinoma and lung adenocarcinoma." (PMID 33299862, 2020). "For lung adenocarcinoma, alterations in EGFR, KRAS, and BRAF were comparable between protocol patients and TCGA (data not shown)." (PMID 32914008, 2019). "Analysis of the TCGA (the cancer genome atlas) pan-cancer cohort of lung adenocarcinoma (LuAd) revealed amplification and/or overexpression of c-MYC in up to 20% of LuAd and a significant enrichment for MYC overexpression in KRAS mutant tumours (p = 0.025)." (PMID 31032816, 2019).
lung adenocarcinoma (continued). "A total of 72 patients with lung adenocarcinoma (30 males and 42 females; age 55.9 ± 11.6 years old) who underwent DESCT scanning and EGFR and KRAS testing were included in this study." (PMID 31783917, 2019). "Kirsten rat sarcoma viral oncogene homolog (KRAS) and epidermal growth factor receptor (EGFR) are the two most frequent and well-known oncogene of lung adenocarcinoma." (PMID 31783917, 2019). "Furthermore, the coexpression of activating KRAS mutations and inactivating BRAF mutations in mouse lung cells markedly enhanced tumor initiation, a phenomenon mediated by CRAF kinase activity, and effectively accelerated tumor progression to advanced lung adenocarcinomas." (PMID 29690599, 2018). "Here, we describe a 57-year-old man who was diagnosed with stage IIIB lung adenocarcinoma and EGFR/KRAS/ALK-negative tumors." (PMID 29361925, 2018). "In cohort 1, the HS values of EGFR, KRAS, HER2, BRAF, and PIK3CA were calculated to estimate intratumor genetic heterogeneity in lung adenocarcinoma." (PMID 29518290, 2018). "This study retrospectively investigated microRNA expression profiles, and their clinicopathological implications, in lung adenocarcinoma according to genetic status (EGFR, KRAS, ALK, and triple negative)." (PMID 28035073, 2017). "However, 6–15% of lung adenocarcinoma patients who had never smoked still harbored a KRAS mutation." (PMID 26739511, 2016). "In our study, we also demonstrated that ectopic expression of RMRP promoted the expression of KRAS, FMNL2 and SOX9 in lung adenocarcinoma cell, which were the direct taget gene of miR-206." (PMID 27906963, 2016). "They showed that miR-155, miR-25, and miR-495 were up-regulated only in the EGFR-wild-type/KRAS-wild-type, EGFR-mutant, and KRAS-mutant lung adenocarcinomas, respectively." (PMID 27005669, 2016). "From August 2011 to November 2013, a total of 1772 patients with treatment-naïve lung adenocarcinoma were enrolled as Cohort 1 for EGFR, KRAS, BRAF and HER2 genetic analyses." (PMID 25789627, 2015). "One recent report described an adenocarcinoma of the lung with HRAS Q61L mutation suffering from rapid progression and deterioration suggesting that HRAS mutations in NSCLC tumors might be aggressive and associated with poor overall prognosis, similar to KRAS mutant NSCL." (PMID 26544513, 2015). "Taken together, our findings offer convincing evidence that the mutual exclusivity of mutant KRAS and EGFR in lung adenocarcinoma is dictated by synthetic lethality." (PMID 26047463, 2015). "In future studies, it would be interesting to examine whether NOTCH1 has distinct or differential roles in lung adenocarcinoma cells that harbor other gene mutations, especially the mutations that do not coexist with KRAS mutations in lung cancer cells, for instance, EGFR mutations." (PMID 26491213, 2015). "One of the first and most apparent of these mutually exclusive mutational combinations involves two well-studied proto-oncogenes, KRAS and EGFR, in human lung adenocarcinomas (LUAD)." (PMID 26047463, 2015). "Analyses of five driver genes, including EGFR, KRAS, BRAF, HER2 and EML4-ALK, were performed in patients with treatment naïve lung adenocarcinoma." (PMID 25789627, 2015). "EGFR, KRAS and STK11 are all involved in the regulation of the mTOR signaling pathway, whose dysregulation has been reported to be important to lung adenocarcinoma." (PMID 25106096, 2014).
lung adenocarcinoma (continued). "Here, we review advances in targeted treatment of lung adenocarcinoma with respect to five clinically relevant biomarkers – EGFR, ALK, MET, ROS-1, and KRAS." (PMID 25157335, 2014). "Therefore, we considered that the diagnostic process of ALK rearrangement could be simplified as follows: screening by IHC with iAEP method followed by confirmatory FISH in EGFR and KRAS mutation-negative lung adenocarcinomas." (PMID 23936355, 2013). "Previously, it has been shown that KRAS copy number gains are correlated with increased RAS-GTPase activity in colorectal cell lines and with worse clinical outcome in lung adenocarcinomas." (PMID 22804917, 2012). "We determined AI in both wild type and mutant case for KRAS and EGFR genes among the 45 lung adenocarcinomas with SNP data." (PMID 19826477, 2009). "Similarly, LSD1 inhibitors can resensitize CRPC to AR blockade, but in lung adenocarcinoma, LSD1 inhibition disrupts EGFR and KRAS pathways with variable effects on tumor growth." (PMID 41601922, 2026). "Dose-response assays showed robust, dose-dependent growth inhibition in both EGFR-mutant (PC9) and KRAS-mutant (H358 and A549) lung adenocarcinoma cells, but not in the human bronchial epithelial cell line BEAS-2B." (PMID 41898563, 2026). "KRAS is one of the most frequently mutated oncogenes in non-small cell lung cancer (NSCLC), particularly in lung adenocarcinoma, with mutation rates ranging from 15% to 25%." (PMID 41668807, 2026). "STK11 loss occurs in approximately 15% of lung adenocarcinomas and is associated with a lack of PD-L1 expression, reduced tumor-infiltrating cytotoxic CD8+ T lymphocytes, and resistance to ICI in patients with KRAS mutant NSCLC." (PMID 41514645, 2025). "In lung adenocarcinoma, sustained NICD signaling has been shown to promote the EMT pathway, cancer stemness, metabolic reprogramming, and therapeutic resistance, with a combined effect of the KRAS and EGFR pathways." (PMID 41451346, 2025). "Importantly, oncogenic KRAS signaling was a strong driver of the COX2/PGE2 signaling axis in both mouse and human lung adenocarcinoma, and COX2 inhibition delayed tumor relapse after KRASG12C inhibition." (PMID 38635884, 2024). "Previous research has shown that EGFR mutations and KRAS mutations rarely occur together, and the use of EGFR-targeted drugs alone to treat KRAS-mutant lung adenocarcinoma has not shown significant clinical benefits." (PMID 38734764, 2024). "Patient#B was a 53-year-old male, current smoker, with a lung adenocarcinoma TTF1+ PDL1 0% without EGFR, KRAS, or BRAF mutation or ALK and ROS1 translocation but STK11 mutation." (PMID 37370798, 2023). "Restored miR-34a levels accompanied with KRAS gene knockdown and reduced MAPK signaling in KRAS-mutant cancers, increased apoptosis, and reduced tumor growth in a physiologically relevant mouse model of human lung adenocarcinoma." (PMID 36865093, 2023). "Of the 11 patients with lung adenocarcinoma (LUAD), 6 (54.6%) had at least one actionable mutation, of which 3 (27.3%) were with EGFR mutations, 3 (27.3%) showed KRAS mutations, and none were with BRAF mutations." (PMID 37769655, 2023). "A study of stage IV lung adenocarcinoma patients treated with pembrolizumab as first-line monotherapy showed that KRAS has no prognostic impact on such treatment." (PMID 36675641, 2023). "Patient#A was a 69-year-old male, former smoker, treated for a lung adenocarcinoma TTF1+ without EGFR, KRAS, or BRAF mutation or ALK or ROS1 translocation but an expression of 100% of PDL1 on the tumor cell." (PMID 37370798, 2023). "This was significantly higher than that observed in lung adenocarcinomas with an EGFR mutation, with a KRAS mutation but lacking an ALK mutation, or with either an EGFR or KRAS mutation (all P < .005)." (PMID 35984185, 2022).